RHO (rhodopsin)
Diseases named in the same sentence as RHO in open-access papers (continued):
Sharing a sentence is not in itself a finding about the gene and the disease.
neuroblastoma (3 papers, 2013 to 2024). Neuroblastoma (NB) is the most common solid, extracranial childhood tumor. "Nevertheless, because LPAR1 is involved in the RHO pathway and the genes in this pathway have been found to be frequently mutated in neuroblastoma, we performed further biological characterization of this somatically acquired mutation." (PMID 24147068, 2013). "However, one major finding in one of the reports was frequent activation of the RHO signaling pathway by mutations to inhibit neuritogenesis in neuroblastoma, and LPAR1 is a membrane receptor in this pathway." (PMID 24147068, 2013). "At least 30% of neuroblastoma cases are indeed due to mutations that alter RHO and RAC activity, involved in the migration of neural crest (NC) cells from which neuroblastoma originates." (PMID 34124035, 2021). "Therefore, our study indicates and confirms that the activation of the RHO pathway may play an important role in neuroblastoma, and the shows importance to detect extremely rare mutations for precision therapy for patients with cancers lacking recurrent mutations." (PMID 24147068, 2013).
osteosarcoma (3 papers, 2018 to 2025). A usually aggressive malignant bone-forming mesenchymal neoplasm, predominantly affecting adolescents and young adults. "To determine the RHO GTPases that are induced early in response to CPT, we treated human osteosarcoma U2OS cells for short times (1 h and 2 h), and analyzed RHO GTPase mRNA expression by reverse transcription followed by qPCR (RT-qPCR)." (PMID 30209297, 2018).
protein misfolding diseases (3 papers, 2016 to 2024). "They hypothesized that rhodopsin-associated RP is a protein misfolding disease (also known as a conformational protein disease), in which the misfolding or misassembly of a mutant protein alters its cellular fate and induces cell death." (PMID 39336749, 2024).
amblyopia (2 papers, 2022 to 2025). Decreased vision that results from abnormal visual development. "For clinical genetic testing, physicians can narrow down the testing gene to RHO in patients with an autosomal dominant family history, electronegative ERG with a normal cone system function, and lack of amblyopia." (PMID 36499293, 2022).
cancer-associated retinopathy (2 papers, 2013 to 2024). Cancer associated retinopathy (CAR) is a paraneoplastic disease of the eye associated with the presence of extraocular malignancy and circulating autoantibodies against retinal proteins. "The most specific and sensitive antigen associated with paraneoplastic retinopathy is recoverin, a 23-kDa protein involved in the activation and recovery of guanylate cyclase, which influences rhodopsin function." (PMID 39720375, 2024). "Studies on the retinal photoreceptor degenerative model of cancer-associated retinopathy (CAR) have revealed significantly high levels of rhodopsin phosphorylation." (PMID 23901245, 2013).
frontotemporal dementia (2 papers, 2014 to 2020). Frontotemporal dementia (FTD) comprises a group of neurodegenerative disorders, characterized by progressive changes in behavior, executive dysfunction and language impairment, as a result of degeneration of the medial prefrontal and frontoinsular cortices. "Overexpression in the zebrafish retina, under the rhodopsin promoter, of human WT tau or the P301L mutant tau, which also causes frontotemporal dementia, leads to degeneration and death of the rod photoreceptors." (PMID 32513741, 2020).
glioma (2 papers, 2019 to 2025). A benign or malignant brain and spinal cord tumor that arises from glial cells (astrocytes, oligodendrocytes, ependymal cells). "We found that two types of peaks were all taking part in the fundamental cancer pathways in glioma, including the RHO GTPase cycle and neuronal system, which were enriched in all patients." (PMID 41473442, 2025). "In glioma cells, RHO GTPases including RHOA and RAC regulate cytoskeletal rearrangements resulting in ameboid and mesenchymal cell motility and have been shown to promote migration and growth of glioma cells in vitro and ex vivo." (PMID 31467533, 2019).
Hyperglycemia (2 papers, 2022 to 2026). An increased concentration of glucose in the blood. "Decreased rhodopsin and 11-cis-retinal levels have also been described in diabetic mice after 4 mo of hyperglycemia." (PMID 41266111, 2026). "In hyperglycemia, rhodopsin expression decreases, and rod cells are more sensitive to hyperglycemia." (PMID 36016568, 2022).
intellectual disabilities (2 papers, 2018 to 2021). "RHOA is a member of the RHO GTPase involved in several intellectual disabilities that affect dendritic structure in adult neurons, a phenotype also described in certain DS models or linked to DYRK1A." (PMID 33693642, 2021).
ischemia (2 papers, 2017). A hypoperfusion of the BLOOD through an organ or tissue caused by a PATHOLOGIC CONSTRICTION or obstruction of its BLOOD VESSELS, or an absence of BLOOD CIRCULATION. "A cardinal feature of the ischemia/reperfusion model is the robust loss of neurons as shown by the reduction of rhodopsin and the thinning of retinal layers." (PMID 28370368, 2017). "Also, no alterations could be observed regarding rhodopsin mRNA expression levels in ranibizumab treated eyes compared to the ischemia group (p = 0.426; data not shown)." (PMID 28800629, 2017).
lung carcinoma (2 papers, 2021 to 2023). "In colon and lung cancer cells, ARL4C promotes cell proliferation through ARF6, RAC, RHO, and YAP/TAZ." (PMID 34590580, 2021). "In this article, rhodopsin guanine nucleotide exchange factors (RhoGEF) mediated epithelial cell transformation (ECT) 2 of AT2 cells in the lung could be a common mechanism between IPF and the lung cancer." (PMID 38081956, 2023).
lymphoma (2 papers, 2019 to 2022). A malignant (clonal) proliferation of B- lymphocytes or T- lymphocytes which involves the lymph nodes, bone marrow and/or extranodal sites. "RHO GAPs and GDIs are negative regulators of the RHO GTPases, but to date no recurrent mutations or genetic aberrations have been described in human lymphoma." (PMID 31248017, 2019). "Of note, in ALK+ ALCL they have pro-oncogenic functions because ALK promotes lymphoma cell proliferation and survival by increasing their GTPase activity through the direct phosphorylation of their RHO GEFs VAV1/VAV3." (PMID 31248017, 2019). "Different genetic and epigenetic mechanisms can deregulate the RHO GTPase signaling network in lymphomas and, in general, in human tumors; the variability of alterations found in different tumors reflects the complex regulation of this signaling in normal cells." (PMID 31248017, 2019). "In this review we present the latest advances in the field with particular focus on the role of the most studied typical RHO GTPases such as CDC42, RAC1, and RHOA and the atypical RHOH in the initiation or progression of human lymphomas." (PMID 31248017, 2019).
mastitis (2 papers, 2024). Inflammation of breast tissue during lactation or postpartum due to an obstructed duct or infection. "Notably, the lncRNA-miRNA-mRNA ternary co-expression network of RHO, RCVRN, CSF1R, CAV3, and GATA4 genes is likely to be involved in the regulation of mastitis in Xinjiang brown cattle." (PMID 38674399, 2024). "The network analysis showed that the CSF1R, RHO, RCVRN, CAV3, and GATA4 genes were core nodes, suggesting that these genes could serve as candidate molecular markers for mastitis." (PMID 38674399, 2024).
medulloblastoma (2 papers, 2009 to 2014). A malignant, invasive embryonal neoplasm arising from the cerebellum. "Photoreceptor differentiation has previously been demonstrated in medulloblastoma with retinal S-antigen and rhodopsin antigens detected by immunohistochemistry." (PMID 19936203, 2009).
oral cancer (2 papers, 2015 to 2020). "In oral cancer cells, SNAIL was previously associated with changes in RHO activity and phosphorylation of EZRIN-RADIXIN-MOESIN family, but no precise mechanism was described." (PMID 32664538, 2020). "We observed a strong nuclear staining for RAP1 in CIN 2/3 samples, as previously reported in oropharyngeal SCC cell lines and human oral cancer specimens, and for other small GTPases, such as RHO and RAC1, in premalignant lesions and cervical cancer." (PMID 25856570, 2015).
retinal detachment (2 papers, 2020 to 2021). An eye emergency condition which may lead to blindness if left untreated. "In retinal detachment model, BMSCs were intraocularly transplanted, and then, the retinal morphology, outer nuclear layer (ONL) thickness and rhodopsin expression were studied as well as apoptosis and autophagy of the retinal cells." (PMID 32003125, 2020).
retinal ischemia (2 papers, 2017 to 2019). A ischemic disease that involves the retina. "As detected via immunohistology, retinal ischemia induced a decrease in rhodopsin+ photoreceptor area." (PMID 28800629, 2017).
schizophrenia (2 papers, 2014 to 2024). A major psychotic disorder characterized by abnormalities in the perception or expression of reality. "Analysis of the clusters from the EpiSig pipeline remarked the importance of the RHO GTPase pathway on the regulatory alterations observed in AT-schizophrenia subjects." (PMID 38648100, 2024).
schwannoma (2 papers, 2023 to 2024). A benign, usually encapsulated slow growing tumor composed of Schwann cells. "Lastly, in the Schwannoma, there were 864 downregulated genes and 813 upregulated genes relative to non-tumor tissue that were associated with elastic fibers and RHO/RAC1 GTPases cycles." (PMID 36865335, 2023).
thyroid cancer (2 papers, 2015 to 2017). "Annotated pathways associated with genes from this dataset include hematopoietic stem cell differentiation, thyroid cancer, voltage-gated potassium channels, and RHO GTPase functional pathways." (PMID 28166733, 2017).
type II diabetes (2 papers, 2017 to 2020). "As such, metformin could potentially exacerbate disease progression in rhodopsin RP patients with the P23H mutation and possibly other rhodopsin misfolding mutations, if they are prescribed for type II diabetes." (PMID 28065882, 2017). "For instance, miR-96 is upregulated in the retina of streptozotocin-induced diabetes rats and in the plasma of type-2 diabetic patients, while miR-96 is downregulated in the RHO-mouse retina, a model for common form of inherited blindness." (PMID 32116694, 2020).
viral infection (2 papers, 2013 to 2014). "In this study, the generated photoreceptors were enriched via fluorescence activated cell sorting mediated by viral infection with a construct containing rhodopsin promoter driving GFP expression." (PMID 24146539, 2013). "Although a Ter349Glu RHO mutant is not misfolded in thesemice, a variety of stimuli including disturbances in redox regulation, calciumregulation, glucose deprivation and viral infection can compromise ERhomeostasis." (PMID 25522272, 2014).
acute myeloid leukemia (1 paper, 2026). Acute myeloid leukemia (AML) is a group of neoplasms arising from precursor cells committed to the myeloid cell-line differentiation. "We investigated the expression of ten RHO GTPase genes in bone marrow samples from patients with acute myeloid leukemia (AML) and myelodysplastic neoplasms (MDS) and analyzed TCGA AML data for prognostic associations." (PMID 41927464, 2026).
Arthritis (1 paper, 2024). Inflammation of a joint. "Of these RHO GTPases, RHOA and RAC1 regulate synovial fibroblast behavior and arthritis severity and joint damage in autoimmune arthritis." (PMID 39683640, 2024).
Autoimmunity (1 paper, 2020). The occurrence of an immune reaction against the organism's own cells or tissues. "Herein, we show that monocytic phagocytosis and inflammatory cytokine release along with protein citrullination, a major player in forms of autoimmunity, work to enhance the progression of RD associated with a rhodopsin mutation." (PMID 32151065, 2020). "We also show the presence of known autoimmunity proteins and protein modifications in the rhodopsin Ter349Glu mutant mouse." (PMID 32151065, 2020).
blastoma (1 paper, 2023). A malignant neoplasm composed of undifferentiated cells. "The detected specific genes and splice variants related to the RHO GTPase signaling pathway render themselves to further investigation as potential markers for the differential diagnosis of blastoma and carcinoma cells." (PMID 38132320, 2023).
cardiac arrhythmia (1 paper, 2019). Any disturbances of the normal rhythmic beating of the heart or MYOCARDIAL CONTRACTION. "Rhodopsin-based optogenetics has later been introduced in experimental cardiology studies and used as a tool to photoactivate cardiac contractions or to identify the sites, timing, and location most effective for defibrillating impulses to interrupt cardiac arrhythmias." (PMID 31164614, 2019).
cerebral cavernous malformation (1 paper, 2016). A disorder characterized by malformations in the structure of the capillaries in the brain. "The exact mechanism by which cerebral cavernous malformations arise is still subject to debate, with deregulation of several signalling pathways such as RHO, TGFβ, β-catenin and MEKK3–KLF2 or MEKK3–KLF4 having been demonstrated to be involved in development and progression of the disease." (PMID 27807006, 2016). "Interestingly, FAM65A provides a link between RHO and CCM3, and hyperactivated RHO signalling in endothelial cells has been shown to be a common feature of cerebral cavernous malformations." (PMID 27807006, 2016).
cocaine addiction (1 paper, 2013). "Nevertheless, though the discovery of an effective therapy that addresses all aspects of cocaine addiction continues to elude researchers, the anti-craving effect of RHO shows potential as a component of combined therapy." (PMID 24174979, 2013). "The fact that RHO does not affect priming- or drug-induced reinstatement of cocaine CPP limits its possible usefulness as a natural treatment for cocaine dependence." (PMID 24174979, 2013).
cognitive disorder (1 paper, 2021). A disease affects cognitive processes. "Abnormal activation of RHO proteins has been shown to play a crucial role in cancer, infectious and cognitive disorders, and cardiovascular diseases." (PMID 34359999, 2021).
dilated cardiomyopathy (1 paper, 2023). Cardiomyopathy which is characterized by dilation and contractile dysfunction of the left and right ventricles. "Large scale proteomics (space omics) identified two canonical protein pathways associated to muscle weakness (necroptosis, GP6 signaling/COL6) in SDM and four key pathways (Fatty acid β-oxidation, integrin-linked kinase ILK, Rho A GTPase RHO, dilated cardiomyopathy signaling) explicitly in LDM." (PMID 36835504, 2023). "These were the two SDM-associated pathways, necroptosis, GP6 signaling, and the four LDM-associated pathways, fatty acid β-oxidation, ILK, RHO, and dilated cardiomyopathy signaling that characterize metabolic SOL muscle changes in short vs. long duration mission conditions in spaceflight." (PMID 36835504, 2023).
dry eye (1 paper, 2024). "In ophthalmology, C3G accelerates rhodopsin regeneration following light absorption, ameliorates ocular fatigue, enhances contrast sensitivity, and improves dry eye symptoms through SOD and GSH peroxidase activity." (PMID 39859017, 2024).
erectile dysfunction (1 paper, 2023). Persistent or recurrent inability to achieve or to maintain an erection during sexual activity. "JTE-013 can improve erectile dysfunction by inhibiting the RHO/ROCK kinase pathway and fibrosis." (PMID 37895915, 2023).
hemophagocytic lymphohistiocytosis (1 paper, 2024). "Previously, four variants in the RHO GTPase CDC42 were discovered in patients affected by syndromes generally characterized by neonatal-onset of cytopenia and auto-inflammation, including hemophagocytic lymphohistiocytosis and rash in the most severe form (NOCARH syndrome)." (PMID 39550374, 2024).
Hypovitaminosis (1 paper, 2025). "Hypovitaminosis A is implicated in defective rhodopsin synthesis." (PMID 40802981, 2025).
joint diseases (1 paper, 2019). "Taken together, our results suggest that the effects of GZZSZTW on treating joint diseases might be achieved through the TGFB1/RHO interaction network coupled with other proteins and signaling pathways that were identified in this study." (PMID 31485261, 2019). "Our results suggest that the effects of GZZSZTW on treating joint diseases might be achieved through the TGFB1/RHO interaction network coupled with other proteins and signaling pathways responsible for cartilage development, growth and repair." (PMID 31485261, 2019). "Our findings indicated that the effects of GZZSZTW on treating joint diseases might achieved though the TGFB1/RHO interaction network coupled with other proteins and signaling pathways responsible for chondrogenesis, chondrocyte proliferation and differentiation and cartilage repair." (PMID 31485261, 2019). "Therefore, our results suggest that the therapeutic effects of GZZSZTW on joint diseases might be achieved through the TGFB1/RHO interaction network, which coordinately interact with multiple proteins and signaling pathways responsible for cartilage development, growth and repair." (PMID 31485261, 2019).
liver disease (1 paper, 2016). "Similarly, the inability to efficiently degrade destabilized, aggregation-prone variants of secreted proteins such as rhodopsin and α-1-antitrypsin (A1AT) facilitates their proteotoxic intracellular aggregation linked to retinitis pigmentosa and liver disease, respectively." (PMID 27435961, 2016).
malaria (1 paper, 2013). Malaria is a serious and sometimes fatal disease caused by a parasite that commonly infects a certain type of mosquito which feeds on humans. "This process led to the various number of rhodopsin genes in different metazoan species; for example, body louse has three different rhodopsin genes while malaria mosquito has nine, and both of them are insects." (PMID 23476135, 2013). "In insects, malaria mosquito has nine rhodopsin genes while body blouse only has three." (PMID 23476135, 2013).
malignant meningioma (1 paper, 2016). "In our hands, targeting of DLC1-v1 with specific shRNA in KT21cells established from human malignant meningioma resulted in enhanced activity of RhoA/RhoB/RhoC GTPases as shown in active RHO pull down assay and increased cell migration in scratch assay." (PMID 27614886, 2016).
meningioma (1 paper, 2016). A generally slow growing tumor attached to the dura mater. "Transfection of KT21 meningioma cell line with shRNA targeting DLC1 isoform 1 resulted in increased activation of RHO-GTPases assessed with pull-down assay, enhanced cell migration observed in scratch assay as well as slight increase of cell metabolism determind by MTT test." (PMID 27614886, 2016).
neuritis (1 paper, 2015). A neuropathy arising from inflammation of one or more nerves. "In presence of NGF, these cells are characterized by enhanced expression of NGF-receptors and rhodopsin, the specific marker of photoreceptor and better cell survival, as well as neuritis outgrowth." (PMID 25897972, 2015).
ocular toxoplasmosis (1 paper, 2021). Ocular toxoplasmosis is an infection in the eye caused by the parasite, Toxoplasm a gondii. "The literature on autoreactivity against retinal components in the context of ocular toxoplasmosis encompasses the response against S-antigen (arrestin), rhodopsin, inter-photoreceptor-binding protein (IRBP) and extracts from human, bovine or primate retina." (PMID 34054794, 2021).
oral squamous cell carcinoma (1 paper, 2024). "VAV2 is an activator of RHO GTPases that promotes and maintains regenerative proliferation-like states in normal keratinocytes and oral squamous cell carcinoma (OSCC) cells." (PMID 38374399, 2024).